MIR532 (microRNA 532)
Synonyms: hsa-mir-532; MIRN532; mir-532
Gene: MicroRNA gene on chromosome X (50,003,148 to 50,003,238, forward strand). Ensembl gene ENSG00000207758.
Gene Ontology:
Biological process: miRNA-mediated post-transcriptional gene silencing
Homologues: Orthologues: chimpanzee ptr-mir-532 (100% identical), guinea pig MIR532 (92% identical), mouse Mir532 (92% identical), macaque mml-mir-532 (86% identical), pig ssc-mir-532 (80% identical), rat Mir532 (80% identical). Paralogues in human: MIR188 (64% identical), MIR660 (55% identical).